TRAJ37 (T cell receptor alpha joining 37)
Gene: T-cell receptor joining (J) gene on chromosome 14 (22,503,750 to 22,503,814, forward strand). Ensembl gene ENSG00000278661.
Diseases named in the same sentence as TRAJ37 in open-access papers:
TRAJ37 is named in the same sentence as 2 diseases in open-access papers, as found by Europe PMC text mining. Sharing a sentence is not in itself a finding about the gene and the disease. The quoted sentences say what the papers report.
Sepsis (1 paper, 2024). Sepsis is defined as life-threatening organ dysfunction caused by a dysregulated host response to infection. "In addition, TRAV27 was over-represented, while TRAV8-1 and TRAJ37 were down-regulated in the E-SEP group compared to the Y-SEP group, which might indicate abnormalities in TCR repertoires in elderly patients with sepsis." (PMID 38909272, 2024).
TRAJ37 also shares sentences with these, for which no sentence is quoted: Allergy (1 paper).